CST3 (cystatin C)
Description:
As an inhibitor of cysteine proteinases, this protein is thought to serve an important physiological role as a local regulator of this enzyme activity.
Synonyms: ADLDWA; ARMD11; HEL-S-2
Tractability: Small molecule: a structure with a bound ligand is known; it has a high-quality binding pocket. Antibody: UniProt places it where antibodies can reach, with high confidence; its Gene Ontology location is reachable by antibodies, with high confidence; UniProt predicts a signal peptide or a membrane-spanning region. PROTAC: its protein half-life has been measured.
Gene: Protein-coding gene on chromosome 20 (23,626,706 to 23,638,556, reverse strand). Ensembl gene ENSG00000101439.
Subcellular location: Secreted
Subcellular location (Human Protein Atlas): Golgi apparatus; Vesicles; Predicted to be secreted
Pathways (Reactome):
Metabolism of proteins: Amyloid fiber formation; Post-translational protein phosphorylation; Regulation of Insulin-like Growth Factor (IGF) transport and uptake by Insulin-like Growth Factor Binding Proteins (IGFBPs)
Immune System: Neutrophil degranulation
Gene Ontology:
Molecular function: amyloid-beta binding; cysteine-type endopeptidase inhibitor activity; endopeptidase inhibitor activity; identical protein binding; peptidase inhibitor activity; protease binding; protein binding
Biological process: defense response; negative regulation of blood vessel remodeling; negative regulation of collagen catabolic process; negative regulation of elastin catabolic process; negative regulation of extracellular matrix disassembly; negative regulation of proteolysis; regulation of tissue remodeling; supramolecular fiber organization; immune response
Cellular component: extracellular exosome; extracellular region; Golgi apparatus; plasma membrane; cytoplasm; endoplasmic reticulum; endoplasmic reticulum lumen; ficolin-1-rich granule lumen; tertiary granule lumen; vesicle
Genetic constraint (gnomAD): Loss-of-function variants: 9 observed, 6.46 expected, observed/expected ratio (o/e) 1.39, 90% interval 0.81 to 1.91. That is too few expected variants to judge how well the gene tolerates losing a copy. Missense variants: 162 observed, 128.9 expected, observed/expected ratio (o/e) 1.26, 90% interval 1.11 to 1.43. Synonymous variants: 69 observed, 56.43 expected, observed/expected ratio (o/e) 1.22, 90% interval 1.01 to 1.49.
Gene-disease validity (ClinGen):
ClinGen rates the evidence that CST3 causes each of these diseases.
leukodystrophy, adult-onset, autosomal dominant, without amyloid angiopathy (autosomal dominant): Limited.
Homologues: Orthologues: chimpanzee CST3 (100% identical), macaque CST3 (97% identical), rat Cst3 (69% identical), mouse Cst3 (68% identical), pig CST3 (67% identical), rabbit CST3 (44% identical), rat Cst5 (41% identical), mouse Cst5 (38% identical), rat Cyss (38% identical), rat Cyssl1 (35% identical), tropical clawed frog cst3 (34% identical), rat AABR07054232.1 (29% identical), and 7 more. Paralogues in human: CST2 (57% identical), CST1 (55% identical), CST4 (55% identical), CST5 (49% identical), CST6 (35% identical), CST8 (31% identical), CST7 (30% identical), CST11 (26% identical), CSTL1 (25% identical), CST9L (24% identical), CST9 (19% identical).
Diseases named in the same sentence as CST3 in open-access papers:
CST3 is named in the same sentence as 493 diseases in open-access papers, as found by Europe PMC text mining. Sharing a sentence is not in itself a finding about the gene and the disease. The quoted sentences say what the papers report.
chronic kidney disease (289 papers, 2008 to 2026). Impairment of the renal function secondary to chronic kidney damage persisting for three or more months. "Urinary cystatin C correlated with tubular damage and increased risk of chronic kidney disease during follow-up." (PMID 42072742, 2026). "Elevated cystatin C has been linked to an increased risk of developing chronic kidney disease (CKD), which is itself a well-established risk factor for all-cause and cardiovascular mortality." (PMID 40983592, 2025). "Glucitol level was estimated to be associated with end-stage renal disease, risk factors and latent variable for kidney function (creatinine, cystatin C, β2-microglobulin)." (PMID 40520523, 2025). "In terms of diagnostic accuracy and prognostic value, cystatin C has been found to outperform serum creatinine in identifying the early stages of chronic kidney disease and predicting unfavourable outcomes, such as renal failure and death." (PMID 39044229, 2024). "The CST3 gene product, Cystatin-C, has, however, been shown to add to creatinine’s estimate of renal function and Cystatin-C strengthens the association of eGFR with end-stage renal disease and mortality." (PMID 37982669, 2024). "The measurement of cystatin C has been recommended to enhance chronic kidney disease (CKD) detection and risk stratification in clinical practice." (PMID 38799784, 2024). "One recent study also found that cystatin C independently predicted major cardiovascular events, the development of chronic kidney disease, and cardiovascular and all-cause mortality." (PMID 39409080, 2024). "A higher stage of chronic kidney disease and a lower concentration of cystatin C-based-eGFR have also been associated with ALS risk, indicating a potential explanatory mechanism for the link between hypertension and ALS." (PMID 38878106, 2024). "The diagnostic value of serum creatinine and cystatin c in evaluating glomerular filtration rate in patients with chronic kidney disease: a systematic literature review and meta-analysis." (PMID 37635222, 2023). "We investigated the associations between estimated chronic kidney disease (CKD), based on the Chronic Kidney Disease Epidemiology Collaboration (CKD-EPI) cystatin C equation, and the risk at onset and prognostic value of CKD for ALS." (PMID 37949878, 2023). "Diverse studies have linked cystatin C to chronic conditions such as end stage renal disease, cardiovascular disease, and more recently impaired cognition." (PMID 37323925, 2023). "Studies have shown that cystatin C is more accurate than creatinine in detecting the initial stages of chronic kidney disease and in predicting the risk of adverse outcomes such as kidney failure and death." (PMID 37509111, 2023). "Cystatin C has been used as a biomarker for cardiovascular risk associated with chronic kidney disease." (PMID 36835011, 2023). "This cohort study compares the use of cystatin C vs creatinine level for detection of high-risk chronic kidney disease." (PMID 36282503, 2022). "Recent data suggest the benefits of GFR calculated with serum cystatin C for evaluation of early risk for end-stage renal disease." (PMID 35208542, 2022). "Cystatin-C (Cys-C) improves the risk classification of patients with chronic kidney disease, death, cardiovascular disease, and end-stage renal disease." (PMID 36042904, 2022). "Cystatin-C is a known risk factor for Chronic Kidney Disease (CKD), but here it was associated as a risk factor for 156 of the 209 diseases." (PMID 36535980, 2022). "It has been reported that the GFR, when estimated by cystatin C, has a better risk stratification capability for mortality and end-stage renal disease than that estimated by serum creatinine." (PMID 33828483, 2021). "Conclusions: 25-OH-vitamin D deficiency and thyroid disorders are exhibited in chronic kidney disease patients and the severity of the former rises with disease progression, as indicated by elevated cystatin C levels." (PMID 33401560, 2021).
chronic kidney disease (continued). "Several studies have shown a very close relationship between cystatin C and cardiovascular events, especially cardiac death and all-cause mortality, among different cohorts, such as patients with chronic kidney disease(CKD) and the elderly people." (PMID 33304930, 2020). "Recent meta-analyses have shown that cystatin C can be favorable alone or combined with creatinine to predict mortality risk and end-stage renal disease (ESRD) in various populations." (PMID 32486490, 2020). "Meanwhile, it has been demonstrated that the addition of a cystatin C-based equation improves overall risk classification for death, cardiovascular disease, and end-stage renal disease." (PMID 33161898, 2020). "For instance, rs911119 located in the CST3/CST4/CST9 gene cluster was reported previously associated with chronic kidney disease in a European population." (PMID 30704471, 2019). "The use of cystatin-C to calculate eGFR is suggested by some as an alternative measure of eGFR due to its increased association with risk of death and progression to end-stage renal disease." (PMID 30563479, 2018). "Chronic kidney disease defined by a triple marker panel (serum creatinine, serum cystatin C, and albuminuria) was strongly associated with moderate DR in an Asian population with diabetes." (PMID 30477167, 2018). "The clinical utility of cystatin-based eGFR was also demonstrated in another clinical study in which only the cystatin C-based chronic kidney disease definition was an independent risk predictor for cardiovascular events." (PMID 26347889, 2015). "Prospective studies have shown in various scenarios that patients with increased cystatin C are at a higher risk of developing both CVDs and chronic kidney disease (CKD, 5)." (PMID 24478035, 2014). "After using clinical categories of estimated GFR based on chronic kidney disease stage, only cystatin C remained significantly associated with the CMBs." (PMID 24925313, 2014). "Plasma cystatin C is a marker for chronic kidney disease, a disease strongly associated with an increased risk for cardiovascular disease." (PMID 23630624, 2013). "Cystatin C also provides numerous other informations, which is why it is important in distinguishing patients with a high degree of risk for complications and poor outcome in chronic renal failure." (PMID 36983618, 2023). "Additionally, there was a second-highest risk group for end-stage renal disease that was missed by creatinine alone but detected by cystatin C and the albumin–creatinine ratio." (PMID 37509111, 2023). "Moreover, CHIP has recently been associated with chronic kidney disease (CKD) Population data of the UK biobank indicated a negative association with glomerular filtration rate estimated from cystatin-C." (PMID 35885518, 2022). "Several studies have confirmed that cystatin C can be used as a predictor of all-cause mortality in the elderly population, long-term mortality in patients with severe disease and mortality in patients with chronic kidney disease." (PMID 36545333, 2022). "The early detection of early renal impairment by serum cystatin C could lead to a likely targeted approach in identifying persons at greater risk of complications of chronic kidney disease." (PMID 33401560, 2021). "The aim of this study was to assess the comparative cardiovascular and mortality risk of chronic kidney disease (CKD) using cystatin C-based and creatinine-based equations of the estimated glomerular filtration rate (eGFR) in participants of population-based and disease cohorts." (PMID 33161898, 2020). "Association of plasma potassium with risk of developing chronic kidney disease defined as eGFRcreatinine-cystatin C <60 ml/min/1.73m2 or urinary albumin excretion >30 mg/24h in 5,130 participants of the Prevention of Renal and Vascular End-Stage Disease (PREVEND) study." (PMID 28346526, 2017).
chronic kidney disease (continued). "Previous studies have focused on specific patient groups (e.g. chronic kidney disease), but the association of cystatin C with CI-AKI in more general patient populations remains unknown." (PMID 29312646, 2017). "Several studies have suggested that the addition of cystatin C measurements to creatinine measurements in calculating the eGFR significantly improves the risk classification for death, cardiovascular disease, and end-stage renal disease." (PMID 28977873, 2017). "Peralta el al discussed the probability that cystatin C might be a better parameter for identifying patients with chronic kidney disease at risk of developing cardiovascular complications than a creatinine-based equation." (PMID 22152087, 2011). "It has been described that high cystatin C levels correlate to an extensively increased risk of cardiovascular events in persons who do not meet the criterion of eGRF ≤ 60 mL/min/1.73 m2, a definition of chronic kidney disease." (PMID 22152087, 2011). "Furthermore, chronic kidney disease as measured by estimated glomerular filtration rate or eGFR (a measure that relies on plasma creatinine levels) or cystatin C may also be associated both with Hcy and NfL." (PMID 39969743, 2025). "Plasma cystatin C measurement is superior to creatinine-based methods for estimating the glomerular filtration rate in terms of its greater sensitivity than creatinine as a predictor of cardiovascular risk and for the early diagnosis of early chronic renal disease." (PMID 33129312, 2020). "If bosutinib-induced chronic kidney disease is suspected, renal function should be assessed by urinalysis and cystatin C levels to differentiate from simple elevation of serum creatinine." (PMID 40000571, 2025). "The potential utility of cystatin C, either alone or incorporated into Chronic Kidney Disease Epidemiology Collaboration (CKD-EPI) equations, warrants further investigation as a more accurate biomarker in this population." (PMID 41301477, 2025). "Unfortunately, she did remain in Stage III chronic kidney disease in the remaining right kidney with an estimated glomerular filtration rate of 46 mL/min/1.73 m2 (by CKiD U25 eGFR equation using creatinine and cystatin C)." (PMID 40546339, 2025). "Elevated cystatin C levels have been associated with worse outcomes in a range of clinical scenarios, including coronary artery disease (CAD), acute and chronic HF, and chronic kidney disease." (PMID 41157213, 2025). "Creatinine, cystatin C, and estimated glomerular filtration rate (eGFR) are the primary parameters used for the definition and staging of chronic kidney disease (CKD)." (PMID 40564142, 2025). "Equations such as the Chronic Kidney Disease Epidemiology Collaboration (CKD-EPI) cystatin C improve GFR estimation, alone or combined with creatinine." (PMID 41503314, 2025). "Cystatin C, microalbumin in urine and creatinine ranked within the top five in chronic renal failure, and sex was one of the top features for predicting chronic renal failure across all ancestries (ICD10: N18)." (PMID 39261665, 2024). "Cystatin C eGFRs were calculated at baseline, 12, 24 and 36 months using Chronic Kidney Disease Epidemiology Collaboration (CKD-EPI) cystatin 2012, European Kidney Function Consortium and CKD-EPI Combined 2021 equations." (PMID 40034484, 2024). "Serum cystatin C has been shown to be a risk factor for CAD after the observation that cystatin C independently predicted major cardiovascular events, chronic kidney disease, and cardiovascular and all-cause mortality." (PMID 38245742, 2024). "It was determined that the cystatin C equation was more accurate and precise in the detection of early chronic kidney disease and that the addition of creatinine to the cystatin C equation did not improve its performance." (PMID 39199326, 2024).
chronic kidney disease (continued). "In this secondary analysis of the STOP-ACEi trial, we explored the impact of discontinuing or continuing renin–angiotensin system inhibitor therapy in people with advanced chronic kidney disease on cystatin C estimated glomerular filtration rate (eGFR)." (PMID 40034484, 2024). "Kidney function, as assessed by the Chronic Kidney Disease Epidemiology Collaboration glomerular filtration rate equation (2021), cystatin C and 24-hour creatinine clearance, remained stable and within normal limits throughout the study." (PMID 38312776, 2024). "Plasma cystatin C-based estimated glomerular filtration rate (eGFR) was calculated using the chronic kidney disease epidemiology collaboration (CKD-EPI) estimator to determine the prevalence of CKD." (PMID 39056083, 2024). "Studies have also been conducted to determine the value of cystatin C in chronic kidney disease classification." (PMID 37545695, 2023). "A growing body of evidence supports the use of cystatin C in the diagnosis and management of chronic kidney disease." (PMID 37509111, 2023). "It has been shown that cystatin C-based calculations of eGFR predict cardiovascular outcomes, end stage renal disease, and death better than creatinine-based eGFR calculations." (PMID 36759756, 2023). "The Chronic Kidney Disease Epidemiology Collaboration creatinine–cystatin C equation was applied to assess eGFR." (PMID 37212462, 2023). "We assayed the protein expression of cystatin C, another biomarker of chronic kidney disease (constitutively expressed across cell types) in effluents coming from the KOC model." (PMID 37707956, 2023). "It is reported that slight renal injury assessed by cystatin C is also related to cardiovascular disease in patients with chronic kidney disease." (PMID 35284141, 2022). "We recruited 138 Korean subjects and evaluated eGFRcr (derived from Chronic Kidney Disease Epidemiology Collaboration (CKD-EPI) based on creatinine) was compared to eGFRcys based on cystatin C as the reference value." (PMID 36530922, 2022). "Serum cystatin C levels are the most accurate, early, and independent predictors of the development and progression of chronic kidney disease in patients with diabetes mellitus, including latent autoimmune diabetes in adults." (PMID 35928354, 2022). "The eGFR was estimated from serum creatinine and/or cystatin C using the Chronic Kidney Disease Epidemiology Collaboration equations (CKD-EPI)." (PMID 36743175, 2022). "We compared the results calculated with the eGFRcr formula and those of the formula based on both creatinine and cystatin C Chronic Kidney Disease Epidemiology Collaboration (CKD-EPI) eGFR (eGFRcr + cys), to those of the eGFRcys formula." (PMID 36530922, 2022). "Recent studies showed that cystatin C is a valuable marker for acute kidney injury in the pediatric population and even helps to stratify CVD risk in children with chronic kidney disease." (PMID 35208542, 2022). "The estimated glomerular filtration rate (eGFR) was calculated with CKD-EPI (Chronic Kidney Disease Epidemiology Collaboration) Cystatin C formula (2012)." (PMID 34819020, 2021). "Diabetic patients with chronic kidney disease had significantly higher serum creatinine, cystatin C and urine protein levels, and 24-h CrCl." (PMID 33401560, 2021). "The majority of chronic kidney disease patients had elevated serum cystatin C levels that increased in a stepwise manner with disease progression." (PMID 33401560, 2021). "Further, a diagnosis of chronic kidney disease (CKD) stage 2 was made based on an eGFR (estimated glomerular filtration rate) of 70.4 ml/min/1.73 m2 using the CKD EPI cystatin C calculation." (PMID 34217267, 2021). "Chronic kidney disease was previously reported to be strongly associated with LEAD and other markers of kidney function such as cystatin C and β2-microglobulin were shown to be better markers of LEAD risk in patients with kidney diseases." (PMID 33801150, 2021).